XIST (X inactive specific transcript)
Diseases named in the same sentence as XIST in open-access papers (continued):
Sharing a sentence is not in itself a finding about the gene and the disease.
psoriasis (6 papers, 2021 to 2025). An autoimmune condition characterized by red, well-delineated plaques with silvery scales that are usually on the extensor surfaces and scalp. "Several lncRNAs are upregulated in psoriasis, such as MSX2P1, XIST, FABP5P3, KLDHC7B-DT, or SPRR2C, whereas MEG3, GAS5, PRINS or NEAT1 are downregulated in psoriasis." (PMID 38256115, 2024). "Other upregulated lncRNA in psoriasis are MIR31HG, MSX2P1, XIST, FABP5P3, KLDHC7B-DT, or SPRR2C; whereas, MEG3, GAS5, PRINS or NEAT1 are downregulated in psoriasis." (PMID 37628670, 2023).
rheumatoid arthritis (6 papers, 2022 to 2025). A chronic, systemic autoimmune disorder characterized by inflammation in the synovial membranes and articular surfaces. "In contrary, the expression of XIST in cartilage tissues collected from 39 patients with rheumatoid arthritis was found to be upregulated, similarly to the level of STAT3 but in opposite to the level of let-7c-5p." (PMID 35796900, 2022). "Furthermore, XIST is involved in the pathogenesis of SLE and rheumatoid arthritis (RA) and can promote the expression of MMP3 and caspase-3, which are important molecules contributing to KD." (PMID 36829193, 2023).
Alzheimer disease (5 papers, 2020 to 2025). A progressive, neurodegenerative disease characterized by loss of function and death of nerve cells in several areas of the brain leading to loss of cognitive function such as memory and language. "Furthermore, XIST has been linked to complex disorders such as Alzheimer’s disease (AD), neurodegeneration, and neuroinflammation." (PMID 40407589, 2025). "In the context of neurodegeneration, dysregulation of XIST and X chromosome inactivation has been reported in several Alzheimer’s disease (AD) studies." (PMID 34281203, 2021). "In addition, the expression of XIST is significantly abundant in both in vivo and in vitro Alzheimer's disease models." (PMID 33228517, 2020).
diabetes (5 papers, 2017 to 2024). "For the differentially expressed lncRNAs identified, MIR7-3HG, LINC01116, HIF1A, MEG3, XIST, NEAT1, and HHLA3 have been previously associated with some form of diabetes and diabetes-associated complications." (PMID 38326874, 2024). "Patients with T2D had a higher level of XIST expression than those without diabetes." (PMID 35889263, 2022).
diabetic nephropathy (5 papers, 2021 to 2024). "Furthermore, XIST protects podocytes against HG-induced damage, induces autophagy in podocytes, and suppresses the progression of diabetic nephropathy by regulating the miR-30d-5p/BECN1 axis." (PMID 38317244, 2024). "Besides, miR-93-5p was disclosed to be regulated by XIST, thereby protecting against renal interstitial fibrosis in diabetic nephropathy." (PMID 34654473, 2021). "Besides, XIST regulates HG-induced podocyte injury by targeting miR-30/AVEN in diabetic nephropathy." (PMID 33996907, 2021).
membranous nephropathy (5 papers, 2019 to 2024). "XIST targets and downregulates mir-217, a negative regulator of TLR4 and downregulation of XIST alleviated podocyte apoptosis and kidney injury in membranous nephropathy by mir-217/TLR4 axis." (PMID 40176927, 2024). "Another lncRNA is the lncRNA XIST, in which its expression was high in patients with primary membranous nephropathy, and this high expression of lncRNA XIST was due to Ang II treatment that promotes podocyte apoptosis." (PMID 32194418, 2020). "XIST expression is highly expressed in membranous nephropathy, and XIST silencing attenuates podocyte apoptosis." (PMID 33299380, 2020). "The expression of lncRNAs XIST and NEAT1 are significantly increased in glomerular and tubular epithelial cells, and urinary XIST serves as a potential marker for detecting membranous nephropathy." (PMID 31658856, 2019).
myeloproliferative disorder (5 papers, 2017 to 2024). A clonal hematopoietic stem cell disorder, characterized by proliferation in the bone marrow of one or more of the myeloid (i.e., granulocytic, erythroid, megakaryocytic, and mast cell) lineages. "They discovered that XIST induction in four independent transgenic clones consistently corrected the over-production of megakaryocytes and erythrocytes, which are implicated in myeloproliferative disorder and leukaemia." (PMID 38474215, 2024). "XIST induction in four transgenic clones reproducibly corrected over-production of megakaryocytes and erythrocytes, key to DS myeloproliferative disorder and leukemia." (PMID 30518921, 2018). "On the other hand, deletion of XIST in the mice resulted in a highly aggressive myeloproliferative neoplasm with 100% penetrance, indicating tumor-suppressive effects of XIST." (PMID 29100288, 2017). "Furthermore, dysregulation of XIST, RUNX1, SON, ERG and STAT1 was observed, contributing to myeloproliferative disorders." (PMID 38474215, 2024).
neuroblastoma (5 papers, 2017 to 2022). Neuroblastoma (NB) is the most common solid, extracranial childhood tumor. "In the context of pediatric tumors, in neuroblastoma an oncogenic role for XIST has also been determined and related to its ceRNA activity." (PMID 35054794, 2022). "Hasegawa and colleagues have shown that SAF-A binds XIST RNA and is required for localizing Xist RNA to Xi in a mouse neuroblastoma cell line, Neuro 2A." (PMID 28947659, 2017). "In particular, XIST depletion repressed tumor growth in vivo and increased radiosensitivity, arrested cell cycle progression and impeded proliferation of neuroblastoma cells in vitro; mechanistically, XIST modulated L1 cell adhesion molecular (L1CAM) expression by competitively binding to miR-375." (PMID 35054794, 2022). "In neuroblastoma, lncRNA XIST was reported to enhance radioresistance through miR-375/L1CAM axis." (PMID 35600868, 2022).
COVID-19 (4 papers, 2022 to 2023). A disease caused by infection with severe acute respiratory syndrome coronavirus 2. "Thus, XIST is closely associated with T cell-induced immune response and may be differentially expressed after COVID-19 vaccination." (PMID 36936955, 2023). "Examination of the top DEGs enriched and depleted in male versus female COVID-19 Mo/DCs revealed appropriate recovery of Y-linked genes (DDX3Y, EIF1AY, and UTY) and XIST, which enables X chromosome inactivation and, thus, is increased in female cells." (PMID 37606044, 2023). "Furthermore, the effects of MALAT1, NEAT1 and XIST are correlated with COVID-19 severity." (PMID 36052163, 2022). "Reduced levels of XIST in severe cases thus is highly likely to be correlated with CRS and severity in COVID-19 progression." (PMID 36052163, 2022).
esophageal cancer (4 papers, 2019 to 2022). A primary or metastatic malignant neoplasm involving the esophagus. "Another study has verified that the progression of esophageal cancer was promoted by XIST-regulated miR-494/CDK6 axis to activate the JAK2/STAT3 signal pathway." (PMID 32127028, 2020). "A recent study demonstrated the abnormal expression of XIST could contribute to esophageal cancer via miR-494/CDK6 axis." (PMID 32038997, 2019).
leukemia (4 papers, 2018 to 2024). A malignant (clonal) hematologic disorder, involving hematopoietic stem cells and characterized by the presence of primitive or atypical myeloid or lymphoid cells in the bone marrow and the blood. "In summary, this study offers new insights into the mechanism by which XIST regulates leukemia." (PMID 34930117, 2021).
lymph node metastasis (4 papers, 2017 to 2022). "There existed a significant heterogeneity for lymph node metastasis subgroup (I2 = 75.3%, P=0.000) across studies included, therefore the random model was used to analyze the relationship between the expression levels of XIST and lymph node metastasis subgroup." (PMID 29752340, 2018).
primary biliary cholangitis (4 papers, 2024 to 2025). Primary biliary cholangitis (PBC) is a chronic and slowly progressive cholestatic liver disease of autoimmune etiology characterized by injury of the intrahepatic bile ducts that may eventually lead to liver failure. "However, the high expression of XIST has been shown to be associated with primary biliary cholangitis in females, XIST can stimulate the proliferation and differentiation of initial CD4+ T cells, which considered to be the reason for the high incidence of PBC in females." (PMID 39346946, 2024). "Recently, high-expression of XIST in CD4-positive cells and natural killer cells has been suggested to trigger the proliferation of naïve CD4 (+) T cells in primary biliary cholangitis." (PMID 38265097, 2024).
renal cell carcinoma (4 papers, 2021 to 2022). "For instance, lncRNA XIST is capable of inducing p21 through interaction with miR-106b-5p in renal cell carcinoma." (PMID 33618674, 2021). "PrognoScan also showed that XIST played an unfavourable prognostic role in several cancers, including BLCA (OS: Cox P = 0.0192), non-small-cell lung cancer (NSCLC, RFS: Cox P = 0.0084) and renal cell carcinoma (RCC, OS: Cox P = 0.0327)." (PMID 36212008, 2022).
triple-negative breast carcinoma (4 papers, 2022 to 2025). An invasive breast carcinoma which is negative for expression of estrogen receptor (ER), progesterone receptor (PR), and human epidermal growth factor receptor 2 (HER2). "Additionally, in triple-negative breast cancer cells (TNBCs), oleuropein modulates the miR-194/XIST/PD-L1 loop by decreasing PD-L1 and miR-194 levels while upregulating XIST, thereby contributing to its ability to reduce the migration capacity of MDA-MB-231 cells." (PMID 39203892, 2024). "In addition, we studied female MDA-MB-436 and MDA-MB-468 triple-negative breast cancer (TNBC) cells, which express XIST, and found that silencing MUC1-C decreases XIST expression." (PMID 38740827, 2024). "Importantly, XIST can exist in exosomes, and the level of XIST in serum exosomes of patients with recurrent triple negative breast cancer (TNBC) is higher than that of patients without recurrence." (PMID 36309693, 2022).
acute myeloid leukemia (3 papers, 2021 to 2022). Acute myeloid leukemia (AML) is a group of neoplasms arising from precursor cells committed to the myeloid cell-line differentiation. "In addition, ‘PI3K-Akt signaling pathway’36, ‘cell cycle’37, and ‘acute myeloid leukemia’35 pathways have been experimentally confirmed to be related with XIST." (PMID 35322118, 2022).
acute respiratory distress syndrome (3 papers, 2020 to 2021). Progressive and life-threatening pulmonary distress in the absence of an underlying pulmonary condition, usually following major trauma or surgery. "XIST aggravated the inflammatory cell infiltration and degree of fibrosis in LPS-induced acute respiratory distress syndrome in mice." (PMID 33776905, 2021). "Additionally, XIST enhanced lipopolysaccharide- (LPS-) induced acute respiratory distress syndrome by upregulating the levels of interferon regulatory factor 2 by binding to miR-204." (PMID 34512861, 2021).
depression (3 papers, 2019 to 2021). "XIST is highly expressed in lymphoblastoid cells from female patients diagnosed with bipolar disorder or recurrent severe depression as well as postmortem human brains of female psychiatric patients." (PMID 34952924, 2021). "Several lncRNAs have been functionally characterized in previous research on pain or depression, such as XIST, uc.48+, NEAT1, and NONRATT007487.2 in neuropathic pain and DISC2, BACE1-AS, and BDNF-AS in depression." (PMID 34440578, 2021). "We found that XIST belongs to intergenic lncRNA and is closely related to the pathogenesis of T2DM with depression." (PMID 31341180, 2019).
fibrosarcoma (3 papers, 2013 to 2021). A malignant mesenchymal fibroblastic neoplasm affecting the soft tissue and bone. "Induction of the 8p human XIST cDNA transgene in the HT1080 fibrosarcoma cell line has been shown to recruit the PRC1/2 established histone marks, ubH2A and H3K27me3." (PMID 33750950, 2021). "Our previously reported inducible transgenic system in the immortal fibrosarcoma line HT1080 provides a tractable system to study the RNA sequences involved in gene repression by XIST." (PMID 23915978, 2013). "To identify the regions of human XIST essential for recruiting heterochromatic marks we generated a series of overlapping deletions in an autosomal inducible XIST transgene present in 8p of the HT1080 male fibrosarcoma cell line." (PMID 33750950, 2021).
ischemic stroke (3 papers, 2022 to 2024). A stroke disorder caused by obstruction of blood flow to the brain, due to thrombotic (local blood clot formation) or embolic (due to a blood clot or other material traveling from another site) event. "In patients with ischemic stroke, XIST levels showed a decrease during the early stage (48 hours) but rose during the late stage (7 days) post-stroke; however, the overall levels of XIST were negatively correlated with the severity of neurological impairment." (PMID 40789569, 2024). "In ischemic stroke, lncRNA XIST has been proposed to be a potential biomarker for predicting the prognosis of acute cerebral ischemia and a therapeutic target for stroke patients." (PMID 35346266, 2022). "There is a negative correlation between serum levels of lncRNA XIST in ischemic stroke patients and the extent of their neurological impairment." (PMID 38543885, 2024). "XIST regulates the levels of the pro-angiogenic factor integrin α5 (itgα5) and the anti-inflammatory Kruppel-like transcription factor 4 (KLF4) by interacting with microRNA-92a (miR-92a), suggesting its role in modulating angiogenesis and anti-inflammatory activities in ischemic strokes." (PMID 38543885, 2024).
Klinefelter syndrome (3 papers, 2014 to 2024). A sex chromosome disorder caused by the presence of an extra X chromosome in the male karyotype. "Moreover, previous studies have shown that XIST is over-expressed in males diagnosed with Klinefelter syndrome compared to XY controls, suggesting a silencing of many genes on the X chromosome, resulting in dysregulation of X-linked gene expression." (PMID 25006883, 2014). "This hypothesis is supported by the observation that men with Klinefelter syndrome (XXY) and women with triple X syndrome, who have high levels of XIST expression due to their having additional X chromosomes, demonstrate an increase in both antiviral responses and incidence of SLE." (PMID 37733447, 2023).
leiomyoma (3 papers, 2024 to 2025). A well-circumscribed benign smooth muscle neoplasm characterized by the presence of spindle cells with cigar-shaped nuclei, interlacing fascicles, and a whorled pattern. "In fact, the lncRNAs MIAT and XIST have been shown to be potential therapeutic targets in fibroids." (PMID 40862769, 2025). "Additionally, we reported that another lncRNA XIST (X-inactive Specific Transcript) which is overexpressed in leiomyomas acts as a sponge for miR-29c and miR-200c." (PMID 39519092, 2024).
liver fibrosis (3 papers, 2023 to 2026). "Our study used LX‐2 cells (hepatic stellate cells) to construct an IR cell model and found that overexpression of lncRNA XIST could inhibit IR in vitro, so lncRNA XIST may also have a reducing effect on liver fibrosis, but this hypothesis still needs further validation." (PMID 38018594, 2023).
multiple sclerosis (3 papers, 2022 to 2025). A progressive autoimmune disorder affecting the central nervous system resulting in demyelination. "This study investigated the role of XIST in neuronal development, neuroinflammation, myelination, and therapeutic responses within cerebral organoids in the context of Multiple Sclerosis (MS) pathogenesis." (PMID 40407589, 2025). "Similarly, lncRNA XIST upregulates hnRNP A1 in Multiple sclerosis (MS) through the XIST-miR-326-HNRNPA1 signaling axis." (PMID 36339596, 2022).
Myocardial fibrosis (3 papers, 2023 to 2025). "One study suggests that XIST may promote myocardial fibrosis after AMI by sponging miR-155-5p, but there is limited literature on the roles of miR-216a and XIST in AMI." (PMID 38402377, 2024).
oral squamous cell carcinoma (3 papers, 2021 to 2022). "This study investigated salivary XIST expression and the correlation to clinical–pathological data among oral squamous cell carcinoma patients." (PMID 34640640, 2021). "However, XIST has a tumor suppressor role in animal models of oral squamous cell carcinoma and renal cell carcinoma." (PMID 34179019, 2021). "Similar result has been reported for XIST in oral squamous cell carcinoma." (PMID 34179019, 2021).
ovarian tumor (3 papers, 2021 to 2024). "Downregulation of XIST in ovarian tumors is associated with reduced expression of upstream activators JPX and FTX." (PMID 39546568, 2024). "We found that XIST is significantly down-regulated in ovarian tumors, with low XIST expression linked to a higher stemness index and lower overall survival." (PMID 39546568, 2024). "XIST expression is significantly reduced in ovarian tumors, correlating to a higher stemness index and poorer patient survival." (PMID 39546568, 2024). "We also found that XIST downregulation was associated with lower levels of its activators, JPX and FTX, in ovarian tumors." (PMID 39546568, 2024). "We demonstrated that XIST was down-regulated in ovarian tumors, resulting in increased cell stemness composition." (PMID 39546568, 2024). "To determine XIST expression patterns in ovarian tumors, we used The Cancer Genome Atlas (TCGA) and Genotype-Tissue Expression (GTEx) database." (PMID 39546568, 2024). "Low levels of XIST in ovarian tumors indicate more M-CSCs, which are more invasive, and are more likely to cause tumors to become aggressive and metastatic, leading to a lower survival rate for patients with low XIST expression." (PMID 39546568, 2024). "To verify that XIST is expressed when two X-chromosomes are present, we stained an ovarian tumor which as expected showed a single red dot per nucleus indicating expression of XIST and thereby X-inactivation." (PMID 38839795, 2024). "Furthermore, the findings may open up therapeutic avenues for patients with low XIST expression of ovarian tumors." (PMID 39546568, 2024).
Parkinson disease (3 papers, 2021 to 2025). A progressive degenerative disorder of the central nervous system characterized by loss of dopamine producing neurons in the substantia nigra and the presence of Lewy bodies in the substantia nigra and locus coeruleus. "In a separate investigation, elevated serum levels of XIST were associated with the Unified Parkinson’s Disease Rating Scale in patients with Parkinson’s disease." (PMID 40407589, 2025). "In vitro and in vivo models of Parkinson’s disease were established to investigate the effects of the lncRNA XIST/miR-199a-3p/Sp1/LRRK2 axis." (PMID 33494069, 2021). "In summary, the results of the present study showed that lncRNA XIST sponges miR-199a-3p to modulate Sp1 expression and further accelerates Parkinson’s disease progression by targeting LRRK2." (PMID 33494069, 2021). "The results indicated that miR-199a-3p expression was downregulated, whereas that of XIST, Sp1 and LRRK2 were upregulated in Parkinson’s disease." (PMID 33494069, 2021).
testicular cancer (3 papers, 2018 to 2021). A primary or metastatic malignant neoplasm that affects the testis. "Nevertheless, the presence of XIST expression, as well as epigenetic signatures typical of the inactive X chromosome, were proposed as biomarkers for testicular cancers." (PMID 33767982, 2021).
Aortic dissection (2 papers, 2023 to 2025). Aortic dissection refers to a tear in the intimal layer of the aorta causing a separation between the intima and the medial layers of the aorta. "Kaplan–Meier analysis showed that survival was shorter in patients with higher XIST expression than in those with lower XIST expression, suggesting that upregulation of XIST is associated with a poor prognosis in patients with aortic dissection." (PMID 40032652, 2025). "Overexpression of XIST causes the apoptosis and inhibition of VSMC proliferation, which can lead to the development of aortic dissection." (PMID 37896804, 2023).